APBB2 (amyloid beta precursor protein binding family B member 2)
Description:
Plays a role in the maintenance of lens transparency, and may also play a role in muscle cell strength (By similarity). Involved in hippocampal neurite branching and neuromuscular junction formation, as a result plays a role in spatial memory functioning (By similarity). Activates transcription of APP.
Synonyms: FE65L; FE65L1; MGC35575
Tractability: PROTAC: ubiquitination databases record sites on it.
Gene: Protein-coding gene on chromosome 4 (40,810,027 to 41,216,714, reverse strand). Ensembl gene ENSG00000163697.
Subcellular location: Endoplasmic reticulum; Golgi apparatus; Early endosome
Subcellular location (Human Protein Atlas): Mitochondria
Gene Ontology:
Molecular function: protein binding; amyloid-beta binding; molecular adaptor activity
Biological process: negative regulation of cell cycle phase transition; negative regulation of transcription by RNA polymerase II; positive regulation of transcription by RNA polymerase II; intracellular signal transduction; maintenance of lens transparency; regulation of DNA-templated transcription; smooth muscle contraction; synapse organization
Cellular component: early endosome; endoplasmic reticulum; Golgi apparatus; nucleus; cytoplasm; growth cone; lamellipodium; membrane; synapse
Genetic constraint (gnomAD): Loss-of-function variants: 28 observed, 71.09 expected, observed/expected ratio (o/e) 0.39, 90% interval 0.29 to 0.54. The upper end of that interval is the gene's LOEUF score, 0.54, which puts it in group 2 of 6, group 1 being the genes least tolerant of losing a copy. Missense variants: 747 observed, 969.95 expected, observed/expected ratio (o/e) 0.77, 90% interval 0.72 to 0.82. Synonymous variants: 333 observed, 373.59 expected, observed/expected ratio (o/e) 0.89, 90% interval 0.81 to 0.98.
Homologues: Orthologues: chimpanzee APBB2 (99% identical), macaque APBB2 (98% identical), pig APBB2 (95% identical), rat Apbb2 (94% identical), mouse Apbb2 (94% identical), guinea pig APBB2 (93% identical), dog APBB2 (91% identical), rabbit APBB2 (91% identical), tropical clawed frog apbb2 (82% identical), Caenorhabditis elegans feh-1 (24% identical). Paralogues in human: APBB1 (45% identical), APBB3 (27% identical).
Diseases named in the same sentence as APBB2 in open-access papers:
APBB2 is named in the same sentence as 27 diseases in open-access papers, as found by Europe PMC text mining. Sharing a sentence is not in itself a finding about the gene and the disease. The quoted sentences say what the papers report.
Alzheimer disease (8 papers, 2015 to 2025). A progressive, neurodegenerative disease characterized by loss of function and death of nerve cells in several areas of the brain leading to loss of cognitive function such as memory and language. "Traditionally, APBB2 has been regarded as an Alzheimer disease protein associated with cognitive impairment." (PMID 34182542, 2021). "APBB2 overexpression is associated with β-amyloid and has been associated with Alzheimer’s disease." (PMID 36745154, 2022). "Genetic association of APBB2 with late onset Alzheimer disease was reported in 200522." (PMID 32054840, 2020). "The amyloid beta A4 precursor protein-binding, family B, member 2 (APBB2) gene encodes a protein that binds to amyloid beta precursor protein (APP), which is central to the pathogenesis of Alzheimer’s disease." (PMID 25887185, 2015). "Low APBB2 expression may disrupt cellular homeostasis, promoting lipid accumulation in neurodegenerative diseases like Alzheimer’s disease (AD)." (PMID 40733561, 2025). "Thus, the APBB2 gene plays a significant role in APP processing and Alzheimer’s disease pathogenesis." (PMID 40733561, 2025).
Cognitive impairment (4 papers, 2016 to 2022). Abnormal cognition is characterized by deficits in thinking, reasoning, or remembering. "Overexpression of APBB2 promotes the accumulation of β-amyloid, and some of its genetic variants are associated with severe cognitive impairment and late-onset AD." (PMID 35682902, 2022). "In addition, the APBB2 rs13133980 G allele was more highly expressed in centenarians with severe cognitive impairment than in the individuals without cognitive impairment." (PMID 32090979, 2020).
dementia (3 papers, 2022). Loss of intellectual abilities interfering with an individual's social and occupational functions. "In contrast, APBB2, which encodes an amyloid beta precursor-binding protein, has been associated with dementia." (PMID 35627228, 2022). "While markers in APBB2 do not show strong evidence for association with AD risk in GWAS comparing controls with individuals with AD-dementia, the gene represents an interesting functional candidate as APBB2 binds AICD." (PMID 35346299, 2022).
mental disorder (2 papers, 2020 to 2025). A disease that has its basis in the disruption of mental process. "Our study identified multiple risk behaviors associated genes, which have been suggested to be involved in the development of mental disorders, such as APBB2 and DCC." (PMID 32090979, 2020).
neuroblastoma (2 papers, 2006 to 2017). Neuroblastoma (NB) is the most common solid, extracranial childhood tumor. "Interestingly, when compared with neuroblasts, the neuroblastomas have more genes in common with the self-renewing neural stem cells (535 versus 145), among others the neurogenesis genes ASCL1, GSS, STAT3, UTP11L, ENAH, APBB2, CDK5RAP2, and LARGE." (PMID 16989664, 2006).
bladder cancer (1 paper, 2022). "APBB2 plays a dual regulatory role in bladder cancer, mediating the cell cycle through the CDK6 and MET pathways." (PMID 36532732, 2022).
breast carcinoma (1 paper, 2021). "Recent studies have reported that APBB2 is also overexpressed in several tumors, including breast cancer." (PMID 34182542, 2021).
cognitive decline (1 paper, 2021). "In the first one, the authors investigated the polymorphism of the APBB2 gene, of which the over-expression promotes the form of β-amyloid, a major component of senile plaques, and thus could play a significant risk factor in the development of cognitive decline at a later age." (PMID 34847191, 2021).
epilepsy (1 paper, 2025). A brain disorder characterized by episodes of abnormally increased neuronal discharge resulting in transient episodes of sensory or motor neurological dysfunction, or psychic dysfunction. "For example, APBB2 was reported to be associated with aging, ZNF608 with preclinical AD, ARID4A and ARVCF with neuropsychiatric diseases, CNN3 with epilepsy, and BTBD1O with ALS." (PMID 40725187, 2025).
fibromyalgia (1 paper, 2025). A chronic disorder of unknown etiology characterized by pain, stiffness, and tenderness in the muscles of neck, shoulders, back, hips, arms, and legs. "Although differential expression of 421 genes has been documented in the development of fibromyalgia (e.g., HDC, GATA2, and APBB2), genome-wide expression profiling in patients with fibromyalgia did not reveal any alterations within the ECS." (PMID 40699629, 2025).
gastric cancer (1 paper, 2021). A primary or metastatic malignant neoplasm involving the stomach. "This study aimed to elucidate the molecular mechanism and biological function of APBB2 in gastric cancer." (PMID 34182542, 2021).
Glucose intolerance (1 paper, 2021). Glucose intolerance (GI) can be defined as dysglycemia that comprises both prediabetes and diabetes. "Even though APBB2 (amyloid beta A4 precursor protein-binding, family B, member 2) primarily binds to APP, knocking out APBB2 in mice causes glucose intolerance and β-cell dysfunction." (PMID 34002691, 2021).
osteosarcoma (1 paper, 2022). A usually aggressive malignant bone-forming mesenchymal neoplasm, predominantly affecting adolescents and young adults. "For example, miRNA-30a-3p was found to inhibit GC cell proliferation and migration by targeting APBB2; miRNA-539 inhibited osteosarcoma cell proliferation, apoptosis, invasion and migration by targeting TRIAP1." (PMID 36203485, 2022).
Parkinson disease (1 paper, 2013). A progressive degenerative disorder of the central nervous system characterized by loss of dopamine producing neurons in the substantia nigra and the presence of Lewy bodies in the substantia nigra and locus coeruleus. "We were specifically drawn to a group of genes that were significantly dysregulated in blood and brain, including Necab3, Apbb2, App, Psen1, Saa1, Prkcg, Park2, Snca and Prnp, because of their involvement in neurodegenerative diseases, such as Alzheimer’s and Parkinson’s disease." (PMID 24278249, 2013).
viral infection (1 paper, 2025). "Both DUSP26 and APBB2 were downregulated in the MSCs of SRLV-SP goats, suggesting a potential co-regulation in response to viral infection and inflammation." (PMID 40733561, 2025). "Thus, reduced expression of both DUSP26 and APBB2 could potentially amplify dysregulation in APP trafficking, oxidative stress, and cell death signaling in response to viral infection or hypoxia-related stress." (PMID 40733561, 2025).
tumor (6 papers, 2021 to 2025). "Some of them are known to affect cellular growth/proliferation: SHISA3 is a known tumor suppressor, APBB2 plays a role in Alzheimer’s disease and the cell cycle, and UCHL1 promotes cellular proliferation in cancer." (PMID 40930101, 2025). "In our study, the results of the TCGA-GA mRNA dataset analysis showed significant differences in APBB2 expression between normal and tumor tissues." (PMID 34182542, 2021). "Moreover, an evaluation of the TGCA-GA database confirmed that APBB2 expression was higher in the tumor tissue compared to normal tissue." (PMID 34182542, 2021). "Our subsequent experiments demonstrated that miR-30a-3p could suppress APBB2 expression in GA cell lines, indicating that it can attenuate GA development as a tumor suppressor." (PMID 34182542, 2021). "Therefore, exploring the molecular mechanism of APBB2 may provide a novel anti-tumor treatment strategy for GA." (PMID 34182542, 2021).
infection (2 papers, 2007 to 2024). The state of being infected such as from the introduction of a foreign agent such as serum, vaccine, antigenic substance or organism. "This included the APBB2 gene present in regions under selection in the Alfred Nzo, Mopani, and Capricorn populations, which was shown to regulate inflammatory responses during infection with porcine reproductive and respiratory syndrome virus, which is a major respiratory pathogen of pigs." (PMID 38254405, 2024). "While cluster 7 showed a set of genes involved in cell cycle (P29, APBB2, GPS1) and the TGFβ-pathway (BMPR2, THBD) up-regulated 6 hours post infection, no concise network or significant functions/pathways could be identified." (PMID 18047719, 2007).
neurodegenerative disease (2 papers, 2013 to 2025). A disorder of the central nervous system characterized by gradual and progressive loss of neural tissue and neurologic function. "While Necab3, Apbb2, App, Psen1, Prkcg and Saa1 are associated with Aβ accumulation, Park2 and Snca are associated with protein aggregation in AD and PD, as well as other neurodegenerative diseases." (PMID 24278249, 2013). "While APBB2 is primarily studied in the context of neurodegenerative diseases, recent studies suggest potential roles in other tissues, including mammary gland development, due to its involvement in cellular differentiation and signaling pathways." (PMID 40733561, 2025).
APBB2 also shares sentences with these, for which no sentence is quoted: cancer (3 papers); alcohol dependence (1); Anxiety (1); colon cancer (1); cortical dysplasia (1); gastric adenocarcinoma (1); Obesity (1); type 2 diabetes (1); vitamin B12 deficiency anemia (1).